CACNA2D1-AS1 (CACNA2D1 antisense RNA 1)
Gene: Long non-coding RNA gene on chromosome 7 (82,009,177 to 82,029,955, forward strand). Ensembl gene ENSG00000223770.
Gene Ontology:
Biological process: miRNA-mediated post-transcriptional gene silencing